HOXB7 (homeobox B7)
Diseases named in the same sentence as HOXB7 in open-access papers (continued):
Sharing a sentence is not in itself a finding about the gene and the disease.
cancer (continued). "As the HOXB7 methylation, which has already been described in several cancers and has been shown to relate with patient’s prognosis, the search for genes that are hypermethylated in response to HOXB7-binding to DNMT3B is also an important and interesting approach to pursue." (PMID 34063128, 2021). "It is undisputed that deregulated of HOXB7 in multiple types of cancers." (PMID 34303375, 2021). "Of note, our data from genetic depletion of HOXB7 and other reports from genetic inhibition of HOXB7 support the notion that HOXB7 might be a novel and viable target, which can be therapeutically manipulated to treat cancer." (PMID 34303375, 2021). "In vitro and in vivo studies have demonstrated that HOXB7 dysregulation may play an important role in a variety of diseases including cancer." (PMID 34458259, 2021). "To further clarify whether HOXB7 is associated with ICC metastasis, we established a metastasis model in nude mice by injecting cancer cells into the tail vein." (PMID 30664713, 2019). "Two major family members of the MAPK pathway, ERK1/2 and p38α, which were increased in the context of HOXB7 overexpression, may play an important role in GC invasiveness and spread, in part by promoting the cancer cell epithelial mesenchymal transformation." (PMID 27901487, 2017). "Moreover, overexpression of HOXB7 is significantly correlated with cancer progression and poor prognosis." (PMID 28646927, 2017). "Cancer therapy targeted against HOXB7 might be a promising approach for the treatment of HCC metastasis and recurrence." (PMID 28454092, 2017). "HOXB7 has been reported to regulate the invasion and migration of cancer cells." (PMID 28646927, 2017). "The effect of HOXB7 on expression of cancer stem cell markers was evaluated." (PMID 28646927, 2017). "Increased expression of HOXB7 has been reported to correlate with the progression in many cancers." (PMID 27901487, 2017). "HOXB7 could promote cancer cell proliferation and might be an independent prognostic factor for patients with ESCC." (PMID 26076456, 2015). "HOXB7, as a known oncogene, has an important role in various types of cancer." (PMID 24853421, 2014). "The level of HOXB7 mRNA in cancer was found to be negatively correlated with the level of miR-337." (PMID 25183455, 2014). "Our analysis revealed 9 shared genes, with UBE2C, POLQ, RAD51, and HOXB7 being up-regulated and EDNRB, GPD1L, F10, SORBS2, and CXCL12 down-regulated in both cancers." (PMID 41790655, 2026). "Elevated expression of HOXB7 and HOXC6 potentially facilitates cancer progression, leading to the accumulation of cancer cells." (PMID 39980564, 2025). "HOXB7 gene is found to be overexpressed in the MCF7 cell line, and it is involved in several metabolic pathways of cancer." (PMID 39458966, 2024). "It is known to negatively correlate with homeobox protein Hox-B7 (HOXB7), which is overexpressed in ESCC and contributes to cancers’ radioresistance." (PMID 36294743, 2022). "HOXB7 is one member of HOX family genes, which are essential developmental regulators and frequently dysregulated in cancer." (PMID 31568655, 2020). "AURKB, HOXB7, KYNU, and LCP1 are strongly upregulated in CESC, with the first two also upregulated in multiple other cancer types." (PMID 30918060, 2019). "A scatter plot of HOXB7 and bFGF expression in 50 HCC cancer tissues revealed a significant positive correlation (r2=0.4416, P<0.001)." (PMID 28454092, 2017). "HOXB7, a member of the HOX family of homeodomain transcription factors, is a critical developmental regulator of cancer cells." (PMID 27901487, 2017). "The expression levels of CDH3, IGF2BP3, HOXB7, and BIRC5 mRNA in malignant biliary strictures were significantly higher than in benign strictures (P = 0.006, <0.001, <0.001, and 0.001, respectively)." (PMID 27399126, 2016). "Many studies have revealed that homeobox-B7 (HOXB7) and miR-337 play important roles in different types of human cancers." (PMID 24641834, 2014).
cancer (continued). "In particular, the cancer-derived lines all show higher expression of the HOXC genes and of HOXB5 and HOXB7, whilst WMPY-1 expresses HOX genes closer to the 5′ (posterior) end of each HOX cluster." (PMID 24499138, 2014). "By using GST-HOXB7-Sepharose affinity chromatography with cell extracts from several breast epithelial cells, both normal (MCF10A, MCF12A) and cancer (SKBR3), we identified PARP-1 as a HOXB7-interaction partner." (PMID 22844406, 2012). "Our data suggest that measuring IGF2BP3, HOXB7 and NEK2 mRNA levels by RT-PCR in addition to cytology has the potential to improve detection of malignant biliary disorders from brush cytology specimens." (PMID 22879911, 2012). "We hypothesize that the expression of HOXB7 and HOXC6 follows a normal distribution trend during cancer cell occurrence and development." (PMID 39980564, 2025). "HOXB7 and HOXC6 may serve as potential targets for cancer treatment and the development of targeted compounds in the future." (PMID 39980564, 2025). "Similarly, HOXB7 activates ERK1/2 in PC to activate the downstream genes and induce the motility and invasion of cancer cells." (PMID 34617205, 2022). "To determine whether HOXB7 regulates the stemness of HNSCC cells, we detected the expression of cancer stem cell (CSCs) related markers." (PMID 34303375, 2021). "Furthermore, HOXB7 has been reported to facilitate the migration of breast and liver cancer cells by inducing EMT, and ectopic expression of HOXB7 promotes angiogenesis and cell proliferation." (PMID 30664713, 2019). "Only 11% (4/36) of GC patient tissues showed lower HOXB7 expression in cancer tissues relative to paired adjacent noncancerous tissue." (PMID 27901487, 2017). "The level of HOXB7 mRNA in cancer had a negative correlation with the level of miR-337 (r = -0.719, P<0.01)." (PMID 24641834, 2014). "Moreover, the cancer stem cell markers EPCAM and NANOG were up-regulated by HOXB7." (PMID 28646927, 2017).
adenocarcinoma (1 paper, 2021). A common cancer characterized by the presence of malignant glandular cells. "HOXB7 high mRNA expression correlated to a significantly worse OS for all NSCLC patients and when considering adenocarcinoma patients only, whereas squamous NSCLC patients were not affected." (PMID 32830458, 2021).
benign tumors (1 paper, 2008). "TOP2A, ETV4 and BIRC5 showed increased expression in all MPNST samples compared to the benign tumors, in most cases more than 20-fold, whereas HOXB7 showed approximately similar expression levels in the MPNSTs and the benign tumors." (PMID 18522746, 2008). "TOP2A, ETV4 and BIRC5 showed increased expression in all MPNST samples, in most cases more than 20-fold, whereas HOXB7 showed approximately similar expression levels in the MPNSTs and the benign tumors." (PMID 18522746, 2008).
HOXB7 also shares sentences with these, for which no sentence is quoted: glioblastoma (4 papers); oral squamous cell carcinoma (3); acute lymphoblastic leukaemia (2); Alzheimer disease (1); bladder urothelial carcinoma (1); cholangiocarcinoma (1); colon adenocarcinoma (1); colonic carcinoma (1); diabetes (1); gallbladder cancer (1); Hepatic hemangioma (1); Hutchinson-Gilford progeria (1); Hydroureter (1); Hypertension (1); idiopathic pulmonary fibrosis (1); laryngeal carcinoma (1); Luminal A (1); lung squamous cell carcinoma (1); metastasis (1); metastatic cancer (1); mouth neoplasms (1); myelodysplastic syndrome (1); myelofibrosis (1); nasopharyngeal carcinoma (1); neural tube defect (1); neurodegenerative disease (1); oesophageal adenocarcinoma (1); periodontitis (1); placental insufficiency (1); psychiatric disorder (1).
A further 8 diseases each share a sentence with HOXB7 in 1 paper.